SNORD115-39 (small nucleolar RNA, C/D box 115-39)
Synonyms: HBII-52-39
Gene: Small nucleolar RNA gene on chromosome 15 (25,241,746 to 25,241,827, forward strand). Ensembl gene ENSG00000200564.
Gene Ontology:
Biological process: RNA processing
Cellular component: nucleolus
Homologues: Paralogues in human: SNORD115-11 (99% identical), SNORD115-29 (99% identical), SNORD115-36 (99% identical), SNORD115-43 (99% identical), SNORD115-12 (98% identical), SNORD115-16 (98% identical), SNORD115-22 (98% identical), SNORD115-26 (98% identical), SNORD115-44 (98% identical), SNORD115-6 (98% identical), SNORD115-9 (98% identical), SNORD115-10 (96% identical), and 37 more.